GPR37 (G protein-coupled receptor 37)
Diseases named in the same sentence as GPR37 in open-access papers (continued):
Sharing a sentence is not in itself a finding about the gene and the disease.
Sepsis (continued). "These works reported that the activation of GPR37, by its ligand NPD1 or agonist ARU, can protect against bacterial infections, sepsis, and inflammatory pain-like behaviors." (PMID 35625743, 2022). "Therefore, GPR37-based immunotherapy may help to treat sepsis and virus infections." (PMID 33731716, 2021). "In this study, we identified an immunotherapy mechanism for sepsis and malaria by which artesunate and NPD1 activate macrophages to promote phagocytosis via GPR37." (PMID 33731716, 2021). "Our data indicate that activation of GPR37 confers protection in multiple models of sepsis, and ARU can bind GPR37 and induce GPR37-dependent phagocytosis in vitro." (PMID 33731716, 2021). "Sepsis induced by LPS and Listeria in wild-type mice is protected by artesunate (ARU) and neuroprotectin D1 (NPD1), but the protective actions of these agents are lost in Gpr37−/− mice." (PMID 33731716, 2021).
bipolar disorder (3 papers, 2015 to 2023). A disorder of the brain that causes unusual shifts in mood, energy, activity levels and the ability to carry out day-to-day tasks. "Instead, GPR37 appears to play a role in DA neurotoxicity and has been linked to the development of autosomal-recessive juvenile parkinsonism as well as major depressive and bipolar disorders." (PMID 26635605, 2015).
breast carcinoma (3 papers, 2022 to 2024). "Our analysis demonstrated that GPR37, as a hub gene, was up-regulated in both brain and lung metastatic breast cancer cell lines." (PMID 35045088, 2022). "Survival analysis showed that the over-expression of GPR37 and the down-regulation of FPR1 were associated with poor overall survival in breast cancer patients, indicating that these hub genes may potentially be a driver for breast cancer development." (PMID 35045088, 2022). "In publicly accessible data from TCGA breast cancer cohort, the methylation levels of cg00452016 in NNT (rho = -0.16, p value = 2.6e−5) and cg01667837 in GPR37 (rho = -0.19, p value = 6.3e−7) were inversely correlated with their corresponding gene expression." (PMID 37101222, 2023). "There were seven shared hub nodes (FPR2, CXCR4, FPR1, CX3CL1, GPR37, GABBR2 and PLCB1) between metastatic breast cancer cell lines." (PMID 35045088, 2022). "Protein-protein interaction (PPI) analysis revealed seven shared (PLCB1, FPR1, FPR2, CX3CL1, GABBR2, GPR37, and CXCR4) hub genes between brain and lung metastasis in breast cancer." (PMID 35045088, 2022).
demyelinating disease (3 papers, 2021 to 2025). A broad group of disorders that affect the myelin sheaths that cover the neurons. "It was demonstrated that one of the most drastically reduced proteins in the brains of Gpr37/Gpr37L1 double knockout mice was the myelin-associated glycoprotein MAG, suggesting that GPR37 may be a potential drug target for the treatment of demyelinating diseases such as multiple sclerosis." (PMID 40822851, 2025). "In addition, gpr37 may become a potential drug target for the treatment of demyelinating diseases such as multiple sclerosis." (PMID 34938813, 2021).
multiple myeloma (3 papers, 2021 to 2023). "GPR37 expression is low in multiple myeloma cell adhesion models and high in proliferating cells." (PMID 36430912, 2022). "In vitro meddling with the expression of GPR37 altered the activity of Akt and ERK in multiple myeloma cells." (PMID 36430912, 2022).
acute myeloid leukemia (2 papers, 2009 to 2024). Acute myeloid leukemia (AML) is a group of neoplasms arising from precursor cells committed to the myeloid cell-line differentiation. "Hypermethylation of GPR37 is also frequently found in acute myeloid leukemia." (PMID 20015385, 2009).
liver cancer (2 papers, 2023 to 2024). An epithelial or non-epithelial malignant neoplasm that arises from the liver. "Multiple reports have shown that GPR37 can promote tumor development, while other studies have indicated its inhibitory effect on liver cancer." (PMID 39730361, 2024).
lung carcinoma (2 papers, 2022 to 2023). "The GEPIA2 online tool was used to select lung cancer patient information from Genotype‐Tissue Expression (GTEx) and TCGA databases, and differences in GPR37 expression were analyzed in LUAD and LUSC tissues and normal tissues." (PMID 37732632, 2023). "In recent years, the research of GPR37 in lung cancer has also made new progress." (PMID 37732632, 2023). "GPR37 has attracted much attention as a therapeutic target for lung cancer." (PMID 36339610, 2022). "In contrast, the analysis showed that the expressions of GPR37 in the two types of lung cancers were not remarkably divergent from those detected in the control group (p > 0.05)." (PMID 37732632, 2023).
malaria (2 papers, 2021 to 2022). Malaria is a serious and sometimes fatal disease caused by a parasite that commonly infects a certain type of mosquito which feeds on humans. "We identified a novel immunotherapy mechanism for malaria by which activation of GPR37 in macrophages can promote phagocytosis of parasite-infected red blood cells." (PMID 36430912, 2022). "We also found that the 1st-line anti-malaria drug, artesunate (ARU), can bind GPR37, and activation of GPR37 with NPD1 or ARU decreases infection severity and septic death." (PMID 33731716, 2021). "Mice lacking Gpr37 exhibited increased death and/or hypothermia following challenge by lipopolysaccharide (LPS), Listeria bacteria, and the mouse malaria parasite Plasmodium berghei." (PMID 33731716, 2021).
mood disorder (2 papers, 2013 to 2024). A cognitive disorder a disturbance in which the person's mood is hypothesized to be the main underlying feature. "Functional characterization of GPRC5B and GPR37 may provide new insights into the pathophysiology of mood disorder, and potential novel strategies for developing methods for diagnoses and treatment of the disorders." (PMID 24391664, 2013).
Parkinsonism (2 papers, 2015 to 2020). Characteristic neurologic anomaly resulting from degeneration of dopamine-generating cells in the substantia nigra, a region of the midbrain, characterized clinically by shaking, rigidity, slowness of movement and difficulty with walking and gait. "Thus, GPR37 aggregation appears to be a hallmark of parkinsonism (AR-JP and PD) and other, although not all, inclusion-related neurological diseases." (PMID 26635605, 2015).
prostate carcinoma (2 papers, 2017 to 2022). A carcinoma that arises from epithelial cells of the prostate gland. "By quantitative RT-PCR we identified prostate cancer PC-3 cells as having comparatively high levels of GPR37 transcript." (PMID 28623304, 2017).
Arthritis (1 paper, 2022). Inflammation of a joint. "In particular, GPR37 agonists could be utilized to treat pain under different clinical settings, such as postoperative pain after surgery, inflammatory pain after infections and arthritis, and neuropathic pain after nerve injury, diabetes, and traumatic brain injury." (PMID 36430912, 2022).
bone cancer (1 paper, 2025). A primary or metastatic malignant neoplasm affecting the bone or articular cartilage. "Collectively, these findings highlight GPR37 activation as a potential therapeutic strategy for alleviating bone cancer pain through direct and synergistic inhibition of osteoclastogenesis and neuronal hyperexcitability." (PMID 39965073, 2025). "The present study demonstrates that activation of the G protein-coupled receptor 37 (GPR37) by neuroprotectin D1 (NPD1) or artesunate (ARU) alleviates both acute and persistent pain in multiple mouse models of bone cancer." (PMID 39965073, 2025).
brain trauma (1 paper, 2022). "Accumulating evidence supports a protective role of GPR37 against neurodegenerative diseases following brain trauma." (PMID 36430912, 2022).
esophageal cancer (1 paper, 2024). A primary or metastatic malignant neoplasm involving the esophagus. "Our data indicated that elevated GPR37 expression suppressed esophageal cancer cell proliferation, invasion, and migration, whereas decreased GPR37 expression conversely enhanced these cellular processes." (PMID 39730361, 2024). "Our subsequent efforts were aimed at delving deeper into the molecular mechanisms that GPR37 engages with to modulate the progression and radiosensitivity of esophageal cancer." (PMID 39730361, 2024). "In consonance with our hypothesis, the high and low order of ZNF750 expression in the six esophageal cancer cell lines was consistent with GPR37." (PMID 39730361, 2024). "To identify effective ways to increase GPR37 levels in esophageal cancer, we investigated exosomes." (PMID 39730361, 2024). "Therefore, we investigated the biological roles of GPR37 in esophageal cancer." (PMID 39730361, 2024). "Furthermore, co-culture with Exo-GPR37 led to elevated levels of GPR37 in the recipient esophageal cancer cells, with no corresponding change in RNA levels." (PMID 39730361, 2024). "However, research on GPR37 in esophageal cancer is currently lacking." (PMID 39730361, 2024).
heart failure (1 paper, 2022). Inability of the heart to pump blood at an adequate rate to meet tissue metabolic requirements. "A study examining the expression profiles of patients with myocardial infarction found that GPR37 L1 was one of the top genes associated with heart failure and that the loss of GPR37 L1 in mice resulted in significantly higher blood pressure levels." (PMID 35409385, 2022). "Although GPR37 L1 was found to be expressed within the myocardium of patients suffering from heart failure, its expression profile within mouse cardiovascular tissue under normal physiological conditions could not be detected at the protein level." (PMID 35409385, 2022). "However, when male and female mice were challenged with an AngII infusion, only male Gpr37 l1-/- mice displayed evidence of heart failure whereas female Gpr37 l1-/- mice were protected." (PMID 35409385, 2022).
Hypertension (1 paper, 2015). The presence of chronic increased pressure in the systemic arterial system. "Regardless, GPR37 and GPR37L1 remain promising therapeutic targets for the treatment of neurodegeneration and hypertension, respectively, although many additional studies will be necessary to confirm the mechanisms and relevance of these receptors to disease." (PMID 26635605, 2015).
infarction (1 paper, 2025). A localised pathological necrosis of tissue resulting from obstruction of the blood supply usually by a thrombus, an embolus, or vascular torsion. "GPR37 is significantly upregulated after focal cortical infarction and functions as a key negative regulator of progenitor cell dynamics within the cerebral cortex after ischemic injury." (PMID 40822851, 2025).
Infertility (1 paper, 2021). "A single hyperdynamic CpG in GPR37 (cg07376282) was reported as an epigenetic marker for infertility." (PMID 34903243, 2021).
ischemia (1 paper, 2022). A hypoperfusion of the BLOOD through an organ or tissue caused by a PATHOLOGIC CONSTRICTION or obstruction of its BLOOD VESSELS, or an absence of BLOOD CIRCULATION. "During the acute phases of MCAO in mice, GPR37 functions to inhibit cell death and the presence of GPR37 L1 has been demonstrated be neuroprotective within hippocampal slices exposed to chemical ischemia." (PMID 35409385, 2022). "After chemical-induced ischemia, cultured hippocampal slices from mice lacking GPR37 L1 (Gpr37 l1-/-) displayed substantially increased neuronal death, suggesting that GPR37 L1 functions in a neuroprotective manner following ischemia ex vivo." (PMID 35409385, 2022).
Kallman’s Syndrome (1 paper, 2019). "As such, mutations in Gpr37 are candidates when searching for oligogenism associated with Kallman’s Syndrome." (PMID 31143101, 2019).
lentivirus infection (1 paper, 2021). Virus diseases caused by the Lentivirus genus. "Moreover, targeted analyses of the SSC5D, GIMAP2, and GPR37 genes indicate links between immune system elements and lentivirus infection." (PMID 33810360, 2021).
neuroblastoma (1 paper, 2018). Neuroblastoma (NB) is the most common solid, extracranial childhood tumor. "Interestingly, the neuroblastoma lines closely related to SK‐N‐MC express substantial levels of GPR37." (PMID 30260505, 2018).
neuropathic pain (1 paper, 2021). Chronic pain caused by damage to nerve fibers. "On the other hand, activation of GPR37 by PD1 modulates macrophage-mediated phagocytosis by increasing intracellular calcium mobilization related to signal transduction mediated by Gi/o subunits, ERK and PI3K/AKT, all involved in the resolution of pro-inflammatory and neuropathic pain states." (PMID 34638711, 2021).
neuropathy (1 paper, 2022). A disorder affecting the nervous system that manifests with pain, tingling, numbness, and/or muscle weakness. "It will be of great interest to investigate whether activation of GPR37 in sensory neurons can protect against neurodegeneration after neuropathy." (PMID 36430912, 2022).
Polydipsia (1 paper, 2026). Excessive thirst manifested by excessive fluid intake. "GPR37 gene expression around the SFO was significantly higher in SAP-D−/− mice than in WT mice, suggesting that PSAP secretion from microglia activates ERK via GPR37, inducing c-Fos expression and excessive water intake, ultimately driving polydipsia onset and progression." (PMID 41438692, 2026).
rectal cancer (1 paper, 2025). A primary or metastatic malignant neoplasm that affects the rectum. "Studies have found that GPR37 expression is significantly increased in liver metastatic tissues of rectal cancer, accompanied by poor prognosis." (PMID 40443721, 2025). "The mechanism may involve GPR37 activating the Hippo signaling pathway, which promotes glycolysis leading to increased histone lactylation, further causing the upregulation of CXC chemokine ligand (CXCL) 1 and CXCL5, thereby mediating liver metastasis of rectal cancer." (PMID 40443721, 2025).
temporal lobe epilepsy (1 paper, 2021). A localization-related (focal) form of epilepsy characterized by recurrent seizures that arise from foci within the temporal lobe, most commonly from its mesial aspect. "Likewise, increased expression of GPR37 was reported in the high-spiking region of temporal lobe epilepsy patients." (PMID 34301297, 2021).
tumor (19 papers, 2011 to 2025). "In silico deconvolution of GBM transcriptomes reveals a positive correlation between GPR37 expression and infiltration by immunosuppressive myeloid cells, including tumor-associated macrophages (TAMs) and M2-like microglia." (PMID 40822851, 2025). "Conversely, GPR37 exhibits reduced expression in hepatocellular carcinoma and multiple myeloma cell adhesion models, and its downregulation has been linked to tumor progression and an unfavorable prognosis of these tumors." (PMID 39730361, 2024). "Excessive activation of GPR37 has been implicated in aberrant cell proliferation, particularly in tumor cells." (PMID 39633709, 2024). "This conclusion is similar to Wang's and Xie's studies, but is different from Li's research, namely that low levels of GPR37 are associated with tumor progression and poorer patient survival, so further validation is needed." (PMID 37732632, 2023). "GPR37 was significantly associated with the infiltration of macrophages, which are the most prominent inflammatory cells in tumor tissues." (PMID 37837549, 2023). "According to the Expression Atlas, the hypoxia-associated molecules CALB1, DDAH1, GAP43 and GPR37, as well as the tumor markers ART3, ENOL2 and FMOD and the tumor promoter NTNG1, are typically expressed in hematopoietic stem cells." (PMID 32466393, 2020). "The enrichment of M2-polarized immune cells in GPR37-high tumors suggests that the receptor facilitates immune evasion, enabling tumor cells to grow in a permissive microenvironment." (PMID 40822851, 2025). "GPR37 has emerged as a molecule involved in both tumor cell–intrinsic pathways and immunological alterations in the tumor microenvironment." (PMID 40822851, 2025). "siRNA silencing of GPR37 has been employed in various in vitro systems to study its function in tumor biology and neuroinflammation." (PMID 40822851, 2025). "qPCR experiments also demonstrated markedly upregulated expression of SERPINH1 and GPR37 in tumor tissues." (PMID 39052154, 2024). "In recent years, some researchers have discovered that GPR37 is significantly upregulated in tumors and has a certain impact on tumor prognosis." (PMID 39052154, 2024). "The tumor volume and weight of the GPR37 group were higher than those of the vector group (p < 0.001)." (PMID 37732632, 2023). "Based on the analysis of clinical data at our center, we also obtained similar findings, that is, the expression of GPR37 in para‐cancerous tissues of NSCLC was lower than that in tumor." (PMID 37732632, 2023). "The expression levels of GPR37 in the tumor tissues were found to be significantly elevated as compared to their corresponding adjacent para‐cancerous lung tissues (p < 0.001)." (PMID 37732632, 2023). "The results corresponded with RT‐PCR findings, where the expression levels of GPR37 within tumor tissues were notably elevated in comparison with their para‐cancerous tissue counterparts, with statistically significant differences (p < 0.001)." (PMID 37732632, 2023). "Subsequently, through clinical verification, the expressions of GPR37 in different tumor tissues were remarkably higher than that in paired para‐cancerous tissues (p < 0.001)." (PMID 37732632, 2023). "Both tumor and para‐cancerous tissue samples were additionally subjected to IHC analyses, which confirmed a significant difference in GPR37 expression levels between NSCLC and para‐cancerous tissues (p < 0.05)." (PMID 37732632, 2023). "GPR37 can drive the invasion, migration and proliferation of tumor cells, and has a certain anti‐apoptotic effect." (PMID 37732632, 2023). "GPR37 downregulation markedly inhibited the proliferation and migration of the tumor cells both in vitro and in vivo by binding to protein kinase CDK6." (PMID 36430912, 2022). "This duality opens avenues for therapeutic targeting: inhibiting GPR37 could theoretically slow tumor progression while reshaping the immunological niche." (PMID 40822851, 2025).